IL6 (interleukin 6)
Diseases named in the same sentence as IL6 in open-access papers (continued):
Sharing a sentence is not in itself a finding about the gene and the disease.
Cachexia (continued). "Overall, the study also showed that IL-6 is necessary but not sufficient for the induction of cachexia." (PMID 33557173, 2021). "Inhibition of these pro‐cachectic cytokines, such as IL‐6 and TNF‐α, was not effective in treating cachexia and caused unwanted side effects in these patients." (PMID 34096686, 2021). "Treatment with 10 mg/kg/d of L-carnitine significantly decreased the serum levels of IL-6 and IL-1 compared with the cachexia control, but did not decrease the serum level of TNF-ɑ." (PMID 34724970, 2021). "Circulating levels of interleukin 6 (IL6) were not a reliable indicator of cachexia in all mouse models as IL6 elevation seemed specific to the C26 model." (PMID 35008253, 2021). "Indeed, in cachexia proinflammatory cytokines (mainly TNF-α and IL-6) directly influence adipocyte metabolism by decreasing the activity of lipoprotein lipase (LPL), an enzyme that regulates the uptake of circulating triglycerides into adipocytes." (PMID 33809200, 2021). "In clinical trials, the neutralization of circulating IL-6 or TNFα have not proven useful to counteract CC, indicating that other factors are involved in cachexia." (PMID 33255345, 2020). "Unlike circulating IL‐6 cytokine, IL‐6 mRNA in gastrocnemius muscle was not induced by cachexia, nor was it modulated by any treatment." (PMID 31930715, 2020). "Another study assessed the level of IL-6 (protein) in serum samples of 94 people with cachexia and in a group of 16 people not diagnosed with cachexia." (PMID 33327591, 2020). "IL-6 can induce skeletal muscle signal transducer and activator of transcription 3 (STAT3) and extracellular regulated kinase (ERK1/2) in several preclinical cancer cachexia models." (PMID 30918582, 2019). "This antibody also suppressed the IL-6 activation of muscle STAT3 and FIS-1 protein expression during cachexia, suggesting that the intracellular IL-6 signaling targets such as STAT3 may contribute to the regulation of mitochondrial fission." (PMID 30918582, 2019). "Serum concentration of IL-6 was higher in patients with late-stage cachexia than those without cachexia and early-stage cachexia." (PMID 29338749, 2018). "In addition, the serum IL-6 level elevated by tumor burden was also dramatically reduced by SGE administration, supporting the beneficial effects of SGE on cancer-induced cachexia symptoms." (PMID 29662645, 2018). "Recently, IL-6 has been shown to induce and sustain WAT browning in cachexia." (PMID 28677104, 2018). "There is evidence to suggest that IL-6 might promote cancer cachexia by regulating WAT lipolysis in early-stage cachexia and BAT generation in late-stage cachexia." (PMID 30081609, 2018). "Based on these findings, we conclude that chronic inflammation (especially that mediated by IL-6) might promote cancer cachexia by regulating WAT lipolysis in early-stage cachexia and browning in late-stage cachexia." (PMID 29338749, 2018). "To summarize, IL-6 is secreted by TOV21G cancer cells, accelerates autophagy in other cells and may therefore be important in cachexia development." (PMID 28515477, 2017). "Taken together, this work demonstrates that different pro‐cachectic inducers (i.e. IL‐6 and IFNγ/TNFα) activate STAT3 signaling independently and that this signaling can collaborate with the NF‐κB pathway to induce cachexia through activation of target genes, like iNOS." (PMID 28264935, 2017). "Inhibition of IL-6, IL-6 receptor, or STAT3 all reduce cachexia in experimental systems." (PMID 28149280, 2016). "The levels of serum IL-6 and IL-1β in the group receiving high-dose docetaxel increased, whereas the levels of TNF-α in all groups were more or less the same, suggesting that the docetaxel-induced cachexia differs from the tumor-induced cachexia." (PMID 25797259, 2015). "Similar results were found upon treatment of cachectic rodents with anti-myostatin inhibitors, where signs of cachexia were reversed without affecting IL-6 or TNF-α plasma levels." (PMID 25460504, 2015).
Cachexia (continued). "It has been well-documented that a wide variety of cytokines can induce cachexia after prolonged production via multiple mechanisms, and these cytokines include TNF-α, IL-6, leukemia inhibitory factor (LIF), ciliary neurotrophic factor (CNTF) and interferon-γ (IFN-γ)." (PMID 26064446, 2015). "Thus, targeting IL-6, PPAR-γ, and Ang II appears to be an important strategy in control of cachexia." (PMID 24381940, 2013). "Systemic IL-6 over-expression was not sufficient to alter mitochondrial protein expression in the gastrocnemius of ApcMin/+ mice initiating cachexia." (PMID 22769563, 2012). "Recent studies indicate that secretions of proinflammatory cytokines such as interleukin-6 (IL-6) play a crucial role in cachexia development, and that these cytokines are secreted from not only cancer cells but also host cells such as macrophages." (PMID 23326296, 2012). "We previously reported no changes in muscle oxidative damage during cachexia in the ApcMin/+ mouse and currently show no changes in oxidative damage with systemic IL-6 over-expression." (PMID 22769563, 2012). "ApcMin/+ mice were examined during the progression of cachexia, after systemic interleukin (IL)-6r antibody treatment, or after IL-6 over-expression with or without exercise." (PMID 22769563, 2012). "Multivariately, high levels of TNF-α (but not CRP, IL-1ß or IL-6) significantly predicted loss of FFMI, however only in patients with established cachexia at entry." (PMID 22708547, 2012). "As in most cancer patients, food intake is not reduced in C26 cachexia and IL-6 levels are elevated." (PMID 21799891, 2011). "Attenuation of IL-6 signaling was effective in blocking the progression of cachexia, but not sufficient to reverse the process." (PMID 21949739, 2011). "Cancer cachexia was accompanied by signs of systemic inflammation, that is, elevated CRP and IL-6." (PMID 20407445, 2010). "Neither BCAA nor BCAA+Di‐Ala mixtures were able to prevent IL6 elevation during severe cachexia." (PMID 40448398, 2025). "Importantly, increased circulating levels of IL-6 and GDF15 were observed even before any reduction in food intake, body weight, or muscle mass, and these levels were further elevated at the onset of anorexia-cachexia." (PMID 40124481, 2025). "Identifying a downstream target of IL-6 signalling, such as PDK3, could provide a way to uncouple therapeutic effects from unwanted side effects, potentially offering a more effective treatment for the deregulated metabolic processes observed in cachexia." (PMID 40275022, 2025). "In one human study, IL-6 was correlated with right atrial pressure and was not impacted by the presence or absence of cachexia, which might be more applicable to our study population." (PMID 41284707, 2025). "However, this event was not sufficient to prevent the development of severe cachexia, suggesting that other mechanisms compensate for the suppression of IL6 induced by antineoplastic agents to promote a severe cachectic condition." (PMID 40448398, 2025). "In this glycolysis shut-down fat body atrophy model, we could not find any involvement of IL-6/upd3 in the disorganization of muscles, unlike what had been shown in the case of tumor-induced muscle wasting in adult Drosophila cachexia models." (PMID 39251827, 2024). "However, no data are available that identify a distinct correlation between TNF-α levels and the magnitude of weight loss nor has a direct link between IL-6 levels and the development of HIVAW and cachexia been shown." (PMID 39301670, 2024). "In addition, raloxifene- and raloxifene/paclitaxel-treated animals revealed no cachexia or peritoneal metastasis, although these therapies did not affect IL-6 levels." (PMID 36672405, 2023). "In addition, serum levels of either S100A8, S100A9, or S100A8/A9 did not correlate with those of IL-6 or TNF-α in PC patients with cachexia (n = 80)." (PMID 37280516, 2023).
Cachexia (continued). "In the piglet model with LPS-induced cachexia, the morphological and ultrastructural damage, and the release of pro-inflammatory cytokines including tumor necrosis factor (TNF)-α, interleukin (IL)-1β, and IL-6 were dynamically elicited in longissimus dorsi muscle." (PMID 37446099, 2023). "Whether reduced tumor growth in vivo was due to the absence of tumor cell IL-6 or to reduced growth substrates (e.g., amino acids, FAs, glycerol) due to reduced cachexia is a complex question under active investigation in our laboratory." (PMID 33851955, 2021). "Similarly, high circulating IL6 levels described as classical cachexia feature were absent in the LLC models, despite apparent weight loss." (PMID 35008253, 2021). "However, inflammatory cytokines associated with cachexia, including tumor necrosis factor (TNF), interleukin (IL)-6, IL-1β, and interferon (IFN)-γ, are unlikely to be considered potential biomarkers associated with cachexia." (PMID 33731895, 2021). "Neither IL6 nor GDF15 therefore seem to be universal cachexia biomarkers in mouse models." (PMID 35008253, 2021). "Furthermore, IL-6 has been shown to inhibit the synthesis of lipids in adipocytes and drives the expression of UCP-1, which is important for the WAT to BAT shift occurring in cachexia, responsible for the increased energy expenditure." (PMID 32660156, 2020). "Finally, in a model of cachexia induced by Trypanosoma cruzi, mice treated with anti-TNF-α antibodies displayed significant attenuation of weight loss, while anti-IL-6 and anti-IFN-γ antibodies had no such effect." (PMID 33329046, 2020). "However, this group showed that unlike the male, significantly higher plasma IL-6 levels in female ApcMin/+ mice electroporated with an IL-6 overexpression plasmid than with a control plasmid did not induce or accelerate cachexia progression." (PMID 33044689, 2020). "When male cancer cachexia and male non-cachexia patients were compared, IL-6 and platelet were significantly elevated in the cachexia group, whereas total protein, albumin, prealbumin, ApoE, lymphocyte counts and hemoglobin were significantly reduced in the cachexia group." (PMID 31788012, 2019). "Thus, circulating factors related to the increased tumor burden, such as IL-6 and MCP-1, may have an important role in cachexia development." (PMID 25789991, 2015). "It was hypothesized that cytokines as IL-1, IL-6, IFN-γ, TNF-α, brain-derived neurotrophic factor, MIC-1 may be involved in the cachexia process, in the imbalance which favors catabolism over anabolism, and in the neurologic and neuropsychiatric manifestations of the disease." (PMID 26337554, 2015). "A comprehensive review of clinical factors associated with cachexia showed little evidence for the association between serum TNF-α and weight loss in cancer, while several studies report an association of plasma IL-6 but not TNF-α with cachexia-associated wasting rather than cancer per se." (PMID 26508820, 2015). "Serum IL-6 levels were higher in patients with cachexia than those without cachexia." (PMID 25010770, 2014). "Receptors for TNF-α, also showed a much lower elevation, indicating that TNF-α signaling may not be as crucial as IL-6 signaling in this particular model of cachexia." (PMID 22361433, 2012). "However, IL-6 regulation of muscle mitochondrial remodeling during the progression of cachexia is not clear and warrants further attention." (PMID 22769563, 2012). "However, the IL-6 regulation of muscle protein turnover during the initiation and progression of cachexia in the ApcMin/+ mouse is not known." (PMID 21949739, 2011). "However, a systemic study of 136 patients with PDAC concluded that IL-6 only correlates with cancer stage and not with cachexia conceding that IL-6 may mediate cachexia but should not be considered as a biomarker." (PMID 37222464, 2023).
Cachexia (continued). "Taken together, changes in IL-6, TNF-α or other pro-inflammatory factors reported previously might be the consequences of the complex tumor-incited immunological responses mediating cachexia, whereas our results support that S100A8, S100A9 and S100A8/A9 are potential drivers of PC-induced cachexia." (PMID 37280516, 2023). "To evaluate local inflammation in skeletal muscle from PDAC patients with or without cachexia, we performed qRT‐PCR to examine mRNA expression of inflammatory cytokines tumour necrosis factor‐alpha (TNF‐α), interleukin‐6 (IL‐6), and interleukin‐1beta (IL‐1β)." (PMID 38725139, 2024). "Physiological levels (those observed in KPC cachexia) of IL6R elicited adipocyte lipolysis, while physiological levels of IL-6 did not, suggesting that IL6R is limiting for signaling in fat and thus must be supplied by trans-signaling." (PMID 33851955, 2021). "In the 16 male patients, median levels of IL-6, TNF-α, and leptin at 6:30 AM didn't differ significantly between the cohorts with and without cachexia." (PMID 25411961, 2014). "Median levels of IL-6, TNF-α, and leptin at 6:30 AM didn't differ significantly between the cohorts with and without cachexia, and the observed trends in level fluctuations were similar to those previously reported." (PMID 25411961, 2014). "Furthermore, intramyocellular lipid content increased with both local inflammation (IL‐6) and systemic inflammation (CRP) in PDAC patients with or without cachexia." (PMID 38725139, 2024). "Indeed, several studies of HF, including HF-induced cachexia, have shown a negative correlation between the irisin concentration and hs-CRP, TNF-alpha, and interleukin-6." (PMID 39200291, 2024). "In contrast, higher TNF-α mRNA expression than in c20-bearing animals, both at tumor sites and in the spleens of c5-bearing mice, suggested that IL-6, not TNF-α, may be a key mediator of cachexia in this model." (PMID 33557173, 2021). "Furthermore, many factors upstream, downstream, and independent of IL-6 and IL6R clearly modulate the development and severity of cachexia in preclinical models." (PMID 33851955, 2021). "However, apart from its early induction in the weight—stable cancer mice, no further increase was observed in SOCS-3 with cachexia progression, highlighting a disconnect between STAT-3 and its downstream negative regulator with chronic IL-6 signaling." (PMID 25789991, 2015). "Besides, median IL-6 and TNF-α levels appeared higher and leptin concentration appeared lower in the cachexia group, albeit without statistical significance." (PMID 25411961, 2014). "In agreement with the results of previous studies, median IL-6 and TNF-α levels in the cohort with cachexia were nearly double those in the cohort without, and leptin levels in the cohort with cachexia were around half those in the cohort without, albeit without statistical significance." (PMID 25411961, 2014).
liver fibrosis (418 papers, 2009 to 2026). "Our study establishes that myeloid-specific Tet2 deficiency exacerbates liver fibrosis through the Ccl2/Ccl8–pMDMs–IL-6–HSCs axis, with Tet2−/− pMDMs driving chemokine production, MDMs infiltration, and HSCs activation." (PMID 41474968, 2026). "PZW mitigated hepatic fibrosis in association with IL-6/JAK2/STAT3 and TGF-β/Smad2/3 signaling pathway inhibition favoring MMP1/TIMP-1 ratio that attenuated collagen deposition and promoted collagen degradation." (PMID 41293246, 2025). "PZW mitigated hepatic fibrosis, with its effect associated with the inhibition of the IL-6/JAK2/STAT3 and TGF-β/Smad2/3 signaling pathways and through raising the MMP1/TIMP-1 ratio." (PMID 41293246, 2025). "In the transformation of chronic hepatitis B (CHB)-associated liver fibrosis to cirrhosis, significantly elevated levels of IL-6 mRNA have been detected in liver tissues, peripheral blood mononuclear cells, and serum of patients with cirrhosis." (PMID 39995661, 2025). "As pro-inflammatory cytokines are directly linked to the development of liver fibrosis 23, the reduction of IL-6, IL-β1 and TNF-α by Tenovin-1 prompted us to test its effects on hepatic fibrosis." (PMID 38993557, 2024). "Recent studies have demonstrated that myeloid-specific interleukin-6 (IL-6) signaling inhibits NAFLD-associated liver fibrosis by delivering exosomes enriched with anti-fibrotic miR-223 to hepatocytes." (PMID 39767572, 2024). "The resolution of liver fibrosis is associated with a decrease in the levels of some cytokines, such as IL-6, IL-1-β, TNF, and TGF-β, in the liver." (PMID 39063116, 2024). "Meanwhile, hepatic IL-6 positively correlates with the extent of liver fibrosis and HSC activation as well, thus suggesting a causative role of Fendrr in HSC activation and liver fibrosis." (PMID 38762176, 2024). "Despite these findings, evidence was provided from diet-induced murine NASH models indicating that IFNγ- or Stimulator of interferon genes (STING)-deficiency attenuates steatosis and liver fibrosis, as well as TNFα and IL-6 mRNA liver expression." (PMID 36768637, 2023). "In the case of IL-6, caution should be taken in the treatment of hepatic fibrosis as it prevents fibrogenesis yet increases the risk of HCC occurrence." (PMID 36978885, 2023). "TLR2 triggered TGF-β1/Smad2/3 and p38/AKT signaling pathways played crucial roles in activating myofibroblasts and promoting the production of IL-6, which exacerbated liver fibrosis caused by C. sinensis." (PMID 36693049, 2023). "In conclusion, the current study found that PGC-1α deficiency deteriorated the I/R-induced liver fibrosis by enhancing the IL-6/JAK2/STAT3 signaling and M2-type macrophage polarization." (PMID 37679346, 2023). "Gene Set Enrichment Analysis (GSEA) showed an enrichment of pathways associated with inflammation and liver fibrosis in SuHx animals, in particular TNFα signaling, IL6-JAK-STAT3 signaling, Interferon alpha (IFNα) and gamma (IFNγ) response." (PMID 35369312, 2022). "Kupffer cells release proinflammatory cytokines such as TNF-α, IL-6, and IL-1, resulting in the activation of hepatic satellite cells, a hallmark event in liver fibrosis." (PMID 34707781, 2021). "The association between inflammatory markers and liver fibrosis is of interest as both higher IL-6 levels and FIB-4 values consistent with ALF have been associated with higher mortality and other health outcomes in different settings." (PMID 34441792, 2021). "Advanced hepatic fibrosis is also associated with oxidative stress, which mediates inflammatory cytokines such as tumor necrosis factor-α and interleukin-6." (PMID 34583706, 2021). "Loss of TNF receptor TNFR1 attenuates liver fibrosis induced by CCl4 or bile duct ligation, accompanied by reduced expression of Col1a1 and Il6 genes and decreased NF-κB activation in liver tissues as well as in isolated HSCs." (PMID 34712238, 2021).